TYR (tyrosinase)
Diseases named in the same sentence as TYR in open-access papers (continued):
Sharing a sentence is not in itself a finding about the gene and the disease.
amelanotic melanoma (5 papers, 2003 to 2023). A melanoma characterized by the complete absence of melanin pigment in the melanoma cells. "In tyrosinase-positive amelanotic melanomas this rate limiting enzyme is inactive because of acidic endo-melanosomal pH." (PMID 19133143, 2009). "In fact, in amelanotic melanomas the most of tyrosinase and of other melanogenic proteins, instead of being transported to the Golgi and endosomes for further processing and glicosilation, due to the acidic environment, are retained in the ER where they are rapidly degraded by proteasome." (PMID 19133143, 2009). "The human amelanotic melanoma A375 cells were also reported to express a very low level of MITF and its target gene TYR." (PMID 38020918, 2023). "Accordingly, tyrosinase mRNA and tyrosinase protein are actually present also in amelanotic melanomas, where no tyrosinase activity and no melanin deposition can be detected." (PMID 19133143, 2009). "Moreover, wild type tyrosinase is retained in the ER and degraded by ERAD in amelanotic melanoma." (PMID 22905195, 2012). "Alternatively, degradation of tyrosinase protein similar to that which occurs in amelanotic melanoma might explain lack of tyrosinase in cultured CCS cells." (PMID 12966428, 2003).
gout (5 papers, 2021 to 2025). A condition characterized by painful swelling of the joints, which is caused by deposition of urate crystals. "Xanthine oxidase and tyrosinase are key enzymes closely associated with gout and skin pigmentation, respectively." (PMID 41464969, 2025).
retinal degeneration (5 papers, 2012 to 2023). Degeneration of the retina. "However, it should be mentioned that FVB/N mice carry two mutations which result in severe vision impairment: a mutation in the tyrosinase gene (TyrC) causing an albino phenotype and the retinal degeneration mutation (Pde6brd/rd11)." (PMID 28376083, 2017). "Collectively, these findings emphasize the role of OTX2 in regulating the human TYR gene, with implications for inter-individual differences in melanin synthesis, retinal development, and function as well as susceptibility to retinal degeneration associated with aging." (PMID 22259223, 2012).
autoimmune disease (4 papers, 2013 to 2023). A disorder resulting from loss of function or tissue destruction of an organ or multiple organs, arising from humoral or cellular immune responses of the individual to their own tissue constituents. "Alopecia areata is considered to be a cell-mediated autoimmune disease, in which autoreactive cytotoxic T cells recognize melanocyte-associated proteins such as tyrosinase." (PMID 24151515, 2013). "VKH disease is an autoimmune disease, in which tyrosinase and tyrosinase-related protein-1 and -2 of melanocytes are primarily identified as autoantigens." (PMID 38137811, 2023). "Recent discovery found genes linking generalized vitiligo to other autoimmune diseases, including TYR gene, which mediates melanin synthesis." (PMID 29362715, 2017). "Moreover, the tyrosinase inhibitor rhododendrol (RD), used as a skin-whitening ingredient, reportedly has the potential to induce leukoderma, a depigmentary autoimmune disease toward melanocytes via binding of RD to melanocyte self-proteins including tyrosinase." (PMID 36671815, 2023).
basal cell carcinoma (4 papers, 2011 to 2021). A carcinoma involving the basal cells. "The function or structural changes in TYR protein (rs1126809) has been associated with basal cell carcinoma or squamous cell carcinoma." (PMID 34373545, 2021).
colon cancer (4 papers, 2018 to 2025). "After transfection of the HINT1 WT or 2KR construct into the A375 colon cancer cell line, the association of HINT1 with MITF and the endogenous expression levels of MITF target genes, including tyrosinase and CDK2, were investigated." (PMID 32636443, 2020). "Loss of MED12 promotes the transition of a mesenchymal phenotype, which is accompanied by chemotherapy resistance in colon cancer patients and resistance to the tyrosinase inhibitor gefitinib in lung cancer." (PMID 30631358, 2018).
leukaemia (4 papers, 2015 to 2024). "We previously developed a cell-based method for metabolite analysis using human tyrosinase-expressing 293T cells (hTYR-293T cells), in which leukemia-inducing phenolic compounds were efficiently converted to their o-quinone metabolites." (PMID 39337478, 2024). "Enzyme assays confirmed the thiopurine leukaemia drug, thioguanine, as a tyrosinase inhibitor with the inhibitory constant of 52 μM." (PMID 29283382, 2017). "In the present study, we examined the activity and expression of tyrosinase in leukaemia cells." (PMID 36230632, 2022). "We have developed the pMHC array to detect CD8+ T-cell populations in leukaemia patients that recognise epitopes within viral antigens (cytomegalovirus (CMV) and influenza (Flu)) and leukaemia antigens (including Per Arnt Sim domain 1 (PASD1), MelanA, Wilms’ Tumour (WT1) and tyrosinase)." (PMID 26492414, 2015).
Strabismus (4 papers, 2014 to 2025). A misalignment of the eyes so that the visual axes deviate from bifoveal fixation. "Nevertheless, there is not yet convincing evidence that TYR mutations contribute to strabismus in humans." (PMID 24579652, 2014). "The unusual axon wiring pattern observed in TYR defective albino animals raises concern that these animals may not be suitable models for human strabismus." (PMID 24579652, 2014).
autoimmune thyroid (3 papers, 2017 to 2025). "Expression of LAMP1 and CD69 in thyroid tissues of AITD patients was upregulated significantly, compared to normal thyroid tissues, while TYR was positively stained only in autoimmune thyroid tissues." (PMID 29362715, 2017). "At the same time, in patients with thyroid autoimmunity, increased ROS levels have been demonstrated which might contribute to modifying tyrosinase or other melanogenic proteins into neoantigens, leading to the appearance of Vitiligo." (PMID 39337081, 2024).
Autoimmunity (3 papers, 2020 to 2024). The occurrence of an immune reaction against the organism's own cells or tissues. "An increased level of homocysteine inhibits tyrosinase and may mediate melanocyte destruction via increased oxidative damage and IL-6 production, triggering autoimmunity and nuclear factor κB activation." (PMID 39337683, 2024). "Homocysteine may mediate melanocyte destruction via increased oxidative damage, interleukin-6 production, and tyrosinase inhibition, triggering autoimmunity and nuclear factor κB activation, and then contributing to the occurrence of vitiligo." (PMID 33093609, 2020).
cataract (3 papers, 2017 to 2024). Partial or complete opacity of the crystalline lens of one or both eyes that decreases visual acuity and eventually results in blindness. "In this study, we analyzed TYR activity in the aqueous humor of 82 eyes of 82 cataract patients." (PMID 28712540, 2017). "Follow-up analysis of the shared loci implicates candidate genes QKI, STK17A, TYR, NSF, and TCF4 likely contribute to the pathophysiology of cataracts and hearing difficulties." (PMID 38632618, 2024).
cobalamin deficiency (3 papers, 2018 to 2024). "The mechanism of hyperpigmentation in vitamin B12 deficiency is believed to be related to increased tyrosinase activity and consequent increased melanin synthesis." (PMID 39070410, 2024). "To assess the effectiveness of melanogenesis under conditions of cobalamin deficiency in vitro, we examined relative melanin content and cellular tyrosinase activity in melanocytes following 24 days of culture with (OH)Cbl(c-lactam) in concentration of 10 μg/mL." (PMID 30235895, 2018). "Our study revealed that melanocytes under conditions of hypocobalaminemia exhibit increased intracellular ROS levels, GSH depletion, and acceleration of melanogenesis via tyrosinase activation." (PMID 30235895, 2018).
depression (3 papers, 2014 to 2024). "GWAS for the HGA/GR ratio identified two genetic loci that mapped to the TAC1 and ASNS genes, which are known to be involved in depression and neurotransmission, while the ratio MET/TYR identified the gene AGBL1 previously linked to neurodegeneration in mice." (PMID 31273200, 2019).
hepatocellular carcinoma (3 papers, 2013 to 2024). A malignant tumor that arises from hepatocytes. "In the present study, intrastriatal transplantation of non-melanogenic human hepatoma HLE cells transfected with tyrosinase cDNA (HLE/tyrosinase) into hemi-parkinsonian mice also markedly improved the asymmetric rotation behavior at day 14 up to 2 months after transplantation." (PMID 23776585, 2013). "Furthermore, non-melanogenic human hepatoma HLE cells transfected with tyrosinase cDNA (HLE/tyrosinase) were transplanted into the striatum of hemi-parkinsonian mice." (PMID 23776585, 2013).
Hyperglycemia (3 papers, 2024 to 2025). An increased concentration of glucose in the blood. "In addition, research demonstrated numerous physiological activities of concentrated P. guajava leaf extract, including the ability to inhibit hyperglycemia, exhibit antioxidant properties, exhibit antibacterial effects and inhibit tyrosinase activity." (PMID 39861590, 2025).
myopia (3 papers, 2021 to 2025). "A previous study has shown that the uveal tyrosinase-dependent dopaminergic system is critically involved in myopia development and tyrosinase inhibition accelerated myopia development in pigmented guinea pigs." (PMID 34830490, 2021). "GSAP and GRM5/TYR genes are associated risk factors for the development of PDS, PG, and myopia." (PMID 36979429, 2023).
neuroblastoma (3 papers, 2016 to 2024). Neuroblastoma (NB) is the most common solid, extracranial childhood tumor. "Melanogenesis is also associated with aggressive neuroblastoma, characterized by higher tyrosinase activity and associated increase in DOPA synthesis." (PMID 30670683, 2019). "Substrate adherent, non-tumorigenic (S-type) neuroblastoma SHEP cells share many characteristics with Schwann cells, including tyrosinase activity specific for melanocytes and expression of fibronectin, vimentin, collagen IV, and SPARC." (PMID 27776337, 2016).
oculocutaneous albinism type 2 (3 papers, 2020 to 2024). Oculocutaneous albinism type 2 (OCA2) is a type of OCA and the most common form of OCA seen in the African population, characterized by variable hypopigmentation of the skin and hair, numerous characteristic ocular changes and misrouting of the optic nerves at the chiasm. "Analyzing the structure of the genomic region of chromosome 15 associated with PWS, we observed the presence of the OCA2 gene associated with type 2 oculocutaneous albinism, tyrosinase-positive." (PMID 38902749, 2024). "Oculocutaneous albinism type II (tyrosinase positive) is caused by biallelic pathogenic variants in the OCA2 gene." (PMID 33138774, 2020).
osteosarcoma (3 papers, 2020 to 2024). A usually aggressive malignant bone-forming mesenchymal neoplasm, predominantly affecting adolescents and young adults. "We also verified the functionality of the HA-MITF protein by transducing an established osteosarcoma cell line, U2OS, known to be available for MITF-induced tyrosinase activation." (PMID 32605315, 2020).
virus infection (3 papers, 2013 to 2022). "In a previous in vitro study of viral infection and melanogenesis, the viral antigen stimulation seemed to hinder the induction of the tyrosinase gene family, at least in the early phase of infection." (PMID 24219276, 2013). "However, in vitro studies may not be reflecting real life and it is not known if virus infection may induce up-regulation of the tyrosinase gene family in the extracutaneous pigmentary system of Atlantic salmon in vivo." (PMID 24219276, 2013).
acute lymphoblastic leukemia (2 papers, 2020 to 2024). Leukemia with an acute onset, characterized by the presence of lymphoblasts in the bone marrow and the peripheral blood. "To obtain more reliable results, we studied both commercially available enzymes (hyaluronidase and tyrosinase), as well as serum hyaluronidase from children diagnosed with acute lymphoblastic leukemia." (PMID 39125044, 2024). "The aim of this study was to evaluate the impact of E. divaricatus root extracts and fractions on proinflammatory serum hyaluronidase and tyrosinase in children diagnosed with acute lymphoblastic leukemia." (PMID 39125044, 2024).
aging (2 papers, 2021). A developmental process that is a deterioration and loss of function over time. "UVR from sunlight, which consists of UV-B and UV-A radiations, induces reactive oxygen species (ROS) and free radical formation, consequently activating proteinases and enzymes such as elastase and tyrosinase, leading to premature skin aging." (PMID 34771125, 2021). "Tyrosinase and elastase are two key enzymes involved in skin deterioration and therefore, inhibition of their activity is a promising protective method against skin aging." (PMID 35723381, 2021).
allergies (2 papers, 2018 to 2023). "In summary, sericin suppresses melanogenesis by inhibition of tyrosinase activity, reduction of inflammation and allergy, and modulation of MITF function." (PMID 30497518, 2018). "In this study, we used in vitro models of allergy induction both in single cells (melanocytes and DCs) and more complex cell systems (artificial skin; MelanoDermTM) to examine the anti-tyrosinase, tolerogenic, and anti-melanogenic properties of urea-extracted sericin." (PMID 30497518, 2018).
atherosclerosis (2 papers, 2012 to 2018). A disease characterized by the build-up of fatty material and calcium deposition in the arterial wall resulting in partial or complete occlusion of the arterial lumen. "Tyrosinase is a polyphenolase enzyme containing copper; therefore, it is believed that inhibition of tyrosinase may prevent oxidation of LDL, thereby inhibiting atherosclerosis." (PMID 22634836, 2012).
atypical rhabdoid teratoid tumours (2 papers, 2023 to 2025). "The atypical rhabdoid teratoid tumours (AT/RT) were further subclassified into three subtypes: SHH (3, 50%), MYC (2, 33.3%) and TYR (1, 16.7%)." (PMID 41033792, 2025). "Atypical teratoid rhabdoid tumors (ATRT) are divided into MYC, TYR and SHH subgroups, suggesting diverse lineages of origin." (PMID 37863903, 2023).
brain tumor (2 papers, 2022 to 2023). "Our use of the v11b4/b6 brain tumor methylation classifier provided confident classifications for tumors as either MYC, SHH, or TYR AT/RT subgroups, even for extracranial RTs." (PMID 35912263, 2022).
chronic kidney disease (2 papers, 2019 to 2021). Impairment of the renal function secondary to chronic kidney damage persisting for three or more months. "It has been suggested that Src tyrosine kinases are involved in the pathogenesis of renal fibrosis, and the selective Src tyrosinase inhibitor PP1 may inhibit fibrosis and have therapeutic potential for the treatment of CKD chronic kidney disease." (PMID 33535441, 2021).
cognitive deficit (2 papers, 2017 to 2022). "To assess the role of BDNF/TrkB pathway in amelioration of cognitive deficit induced by acupuncture, we used specific tyrosinase inhibitor K252α to block BDNF/TrkB pathway." (PMID 28243312, 2017).
contact dermatitis (2 papers, 2020 to 2024). An inflammatory skin condition caused by direct contact between the skin and either an irritating substance or an allergen. "Gel with SNLs: ex vivo drug diffusion, drug deposition studies, antioxidant activity (DPPH assay), in vitro tyrosinase inhibition assay skin irritation test, efficacy against irritant contact dermatitis (BALB/c mice ears)." (PMID 39458602, 2024).
COVID-19 (2 papers, 2022). A disease caused by infection with severe acute respiratory syndrome coronavirus 2. "Kuwanon C is a component of M. alba L. that has been studied previously for its antiviral, antibacterial, antifungal, tyrosinase inhibitory, antioxidant, neuroprotective, and anti-inflammatory effects; however, no efficacy against COVID-19 has yet been found." (PMID 36293371, 2022).
dementia (2 papers, 2022 to 2023). Loss of intellectual abilities interfering with an individual's social and occupational functions. "Neurodegeneration might also be prevented by inhibiting enzymes such as acetylcholinesterase, butyrylcholinesterase, and tyrosinase among patients with dementia." (PMID 36297533, 2022).
dermatitis (2 papers, 2023 to 2024). An inflammatory process affecting the skin. "Although kojic acid, a 3-hydroxy-4-pyrone compound, remains the most extensively researched TYR inhibitor, its usage has been banned in numerous countries due to adverse effects including dermatitis, carcinogenicity, hepatotoxicity, and unspecified mechanisms." (PMID 38921030, 2024). "Additional well-known tyrosinase hyperactivity inhibitors include compounds such as hydroquinone (mutagenic, dermatitis, and irritation), arbutin (unstable), L-ascorbic acid (degradation), kojic acid (carcinogenic), and ellagic acid (solubility)." (PMID 37649388, 2023).
glaucoma (2 papers, 2021 to 2023). Increased pressure in the eyeball due to obstruction of the outflow of aqueous humor. "Of interest, a recent genome-wide association study (GWAS) to determine the polygenic risk score for glaucoma susceptibility and progression identified a significant signal for TYR." (PMID 33808351, 2021). "The allele G, associated with fair skin or eye color, decreased the risk of glaucoma and cataract; and rs1126809, a missense variant in TYR gene significantly associated with three pigmentary traits (ease sunburn, Fitzpatrick scale and phototype score), and with neoplasms and bipolar disorder." (PMID 36672889, 2023).
Hypercalcemia (2 papers, 2020 to 2023). An abnormally increased calcium concentration in the blood. "In response to the increased calcium level in hypercalcemia, this system generates black pigment melanin on the skin via transgenic tyrosinase-mediated enzymatic reaction and thus is ideal for naked-eye detection." (PMID 36906608, 2023).
iris disease (2 papers, 2006 to 2011). "Genetic epistasis experiments introducing a B6 tyrosinase mutation into the congenic strains demonstrated that both the single and double-congenic iris diseases are rescued by interruption of melanin synthesis." (PMID 16827931, 2006). "Moreover, the iris disease appears to be due to the formation of toxic products of the melanin pathway, as deficiency of TYR mitigated the degradation of the iris." (PMID 21976956, 2011). "A significant result in understanding the Tyrp1 and Gpnmb mediated iris disease is that modulating pigment production with tyrosinase (Tyr, a gene essential for pigment production) and hypopigmentation mutations completely rescues iris atrophy and pigment dispersion." (PMID 16827931, 2006).
kidney carcinoma (2 papers, 2016 to 2025). Primary or metastatic malignant neoplasm involving the kidney. "Cytotoxic against the KM12 (colon), A498 (kidney carcinoma), and UO31 (renal) cancer cell lines, acetylcholinesterase (AChE), butyrylcholinesterase (BChE), and tyrosinase (TYR) inhibition activity." (PMID 40363722, 2025).
lung adenocarcinoma (2 papers, 2019). A carcinoma that arises from the lung and is characterized by the presence of malignant glandular epithelial cells. "Focusing on the direct association supported by the literature, the searching results elucidated that for the AC & stage category, only ALCAM, TYR and SART1 are related to lung adenocarcinoma but with very low confidence scores (1.60, 0.25 and 0.25 respectively)." (PMID 30971213, 2019).
malignant rhabdoid tumors (2 papers, 2021 to 2022). "By methylation profiling, all tumors were classified as rhabdoid tumors with a corresponding subclassification within the MYC, TYR, or SHH AT/RT subgroups." (PMID 35912263, 2022).
melanocytic neoplasm (2 papers, 2015 to 2025). "HMB-45, MART-1 (Melan A), S-100, and tyrosinase are almost always diffusely positive in primary melanocytic neoplasms of the CNS." (PMID 26294993, 2015). "These include Melan-A, HMB-45, tyrosinase, and MITF, which are typically specific to melanocytic neoplasms." (PMID 40598734, 2025).